CD4 (CD4 molecule)
Diseases named in the same sentence as CD4 in open-access papers (continued):
Sharing a sentence is not in itself a finding about the gene and the disease.
lupus (continued). "Patients with active SLE have shown an increased amount of CD4+CD25−FoxP3+ T-cells correlating with lupus nephritis." (PMID 34769406, 2021). "Briefly, CD4+ T cells from the peripheral blood of one patient with systemic lupus erythematosus (SLE; n = 9708 cells), one patient with type 1 diabetes (T1D; n = 7042 cells) and one healthy donor (HD; n = 7197 cells) were studied." (PMID 32665635, 2020). "This study aimed to examine the phenotype and function of circulating CD4+Foxp3+ T cells in patients with systemic lupus erythematosus (SLE)." (PMID 32317002, 2020). "In addition, butyrate has also been shown to contribute to CD4 + Foxp3 + T cell induction in vitro, suggesting that this compound may attenuate lupus by altering the balance between Th17 cells and Treg cells." (PMID 33262998, 2020). "CMA has also been implicated to promote antigen presentation on APCs' surfaces and generate hyperactive CD4+ T cells in systemic lupus erythematosus (SLE) models." (PMID 32733448, 2020). "Previous reports have associated increased CMV seropositivity with expansion of CD4 + CD28- T cells in RA, multiple sclerosis (MS) and systemic lupus erythematosus (SLE)." (PMID 32190092, 2020). "IL-10 is known to be elevated in the serum and tissues of patients with systemic lupus erythematosus (SLE) and the expression of IL-10 is activated by Stat3 (signal transducer and activator of transcription 3) in peripheral CD4+ T cells." (PMID 30816218, 2019). "Given that inhibition of glycolysis through CG-5 suppresses CD4+ T cell polarization and alloreactive activation in vitro, we next examined whether inhibition of glucose transport affects the progression of autoimmune phenotypes in lupus-prone mice." (PMID 31057554, 2019). "In a recent study, we demonstrated that bacteria-specific Th1 (IFN-γ producing CD4 T cells) and Th17 (IL-17 producing CD4 T cells) cells played pivotal roles in restraining Hi infection; thus, we first examined Th1 and Th17 responses induced by Hi in the lupus-prone mice." (PMID 31565032, 2019). "In addition, genomic DNA in lupus CD4+ T cells has been found to show DNA hypomethylation." (PMID 31611879, 2019). "Systemic lupus erythematosus (SLE) is a systemic autoimmune disease, in which autoreactive CD4+ T cells play an essential role by providing help to autoantibody-producing B cells both in mice and patients." (PMID 31057554, 2019). "The ability to dampen overall humoral immunity and therefore extend survival by targeting this axis was also confirmed in another lupus-prone mouse model treated with αCD137 Ab, and the suppressed CD4+ T-dependent humoral immune responses may be responsible for these findings." (PMID 31597242, 2019). "The protective effects have been validated in lupus-prone mice treated with a B lymphocyte gene vaccine that codes for IgG1 Fc-pCons, where early and repeated administration of the vaccine delayed proteinuria and enhanced survival remarkably as well as the expansion of Foxp3+ CD4+ Treg cells." (PMID 31379858, 2019). "(ii) Specific types of CD4+ T helper (Th) lymphocytes, namely Th1 and Th17 cells, represent important players in the establishment and course of rheumatoid arthritis (RA), whereas (iii) B cells have emerged as central players in systemic lupus erythematosus (SLE)." (PMID 31396235, 2019). "T cells play a critical role in SLE pathogenesis and previous work has identified alterations in CD4+ T cell subsets in patients with lupus." (PMID 30740104, 2019). "Several investigations have found elevated expression of circulating CXCR5+CD4+ T cells in patients with autoimmune diseases (such as systemic lupus erythematosus (SLE) and Sjogren's syndrome) and infectious diseases (such as hepatitis B and C)." (PMID 30402448, 2018). "In this study, we analyzed the levels and function of CD4+CD69+ Treg cells in patients with systemic lupus erythematosus (SLE)." (PMID 29038617, 2017).
lupus (continued). "A subset of CD27+CD25high Vδ1 T cells, expressing FoxP3 similarly to regulatory CD4+ T cells, was reported in patients with systemic lupus erythematosus (SLE)." (PMID 28713381, 2017). "Anti-IFNAR or anti-NKG2D treatment of B6.MRL/lpr mice remarkably restored Treg cell numbers and ameliorated the lupus disease, confirming the substantial contribution of NKG2D+CD4+ T cells to the decrease in Treg cells observed in SLE patients." (PMID 28455530, 2017). "In order to assess whether HCQ had a dose-dependent inhibitory effect on CD154 expression in SLE patients, various doses of HCQ were used to treat purified CD4+ T cells from lupus patients in vitro for 24 hours, and then stimulated by 1 μg/ml ionomycin for 6 hours." (PMID 28793932, 2017). "Systemic lupus erythematosus (SLE) features a decreased pool of CD4+CD25+Foxp3+ T regulatory (Treg) cells." (PMID 28455530, 2017). "Systemic lupus erythematosus (SLE) is supported by chronic activation of CD4+ T cells supported by both glycolysis and mitochondrial metabolism." (PMID 28303386, 2017). "Patients with active lupus also have similar hypomethylated, autoreactive CD4+ T cells which comprise a novel subset, the size of which is directly related to disease activity, suggesting that these T cells may participate in flares of human lupus as they do in the murine models." (PMID 28620656, 2017). "This study aims to explore effects of 1,25(OH)2D3 and vitamin D receptor (VDR) on peripheral CD4+/CD8+ double‐positive (DP) T lymphocytes in systemic lupus erythematosus (SLE)." (PMID 28063200, 2017). "CD4+ T cells from SLE patients exhibit similar demethylation patterns, as do those from patients with sjögren’s syndrome, subacute cutaneous lupus, and rheumatoid arthritis." (PMID 29018507, 2017). "The importance of T cell PKCδ inactivation in lupus pathogenesis was confirmed by creating a double transgenic mouse strain in which expression of a dominant negative PKCδ (dnPKCδ) is selectively activated in CD4+ T cells by adding doxycycline to their drinking water." (PMID 28620656, 2017). "It has been shown that autoimmune responses in SLE may partly be explained by Regulatory factor X-box 1 (RFX1) downregulation, which results in histone H3 hyperacetylation at the promoter region of CD11a and CD70 genein CD4+ T cells of patients with systemic lupus erythematosus (SLE)." (PMID 27669210, 2016). "Immune disturbances in systemic lupus erythematosus (SLE) may be associated with abnormal homeostasis or defective function of regulatory cells, which has been proved in the study carried on mice susceptible to lupus with genetically modified regulatory CD4+CD25+ cell depletion caused by thymectomy." (PMID 27156107, 2016). "However, although there may be some discrepancies due to variations in phenotype analysis, peripheral regulatory T cells (CD4+CD25+ T cells) seem to play a role in human lupus pathogenesis." (PMID 27635407, 2016). "We also noted that reduced lactoferrin expression on PMN of patients with active systemic lupus erythematosus (SLE) abnormally modulates Th1/Th2 cytokine production by autologous CD4+ T cells." (PMID 27258015, 2016). "Using this strategy, it was shown in human SLE that circulating TFH cells (cTFH) defined as CD4+CXCR5+PD-1+/high and/or ICOS+ T lymphocytes are expanded in lupus patients and their presence correlates with a more severe disease phenotype." (PMID 27635407, 2016). "In murine models of drug-induced lupus erythematosus, it has been shown that mice receiving CD4+ T cells treated with demethylating agents, including procainamide and hydralazine, develop a SLE-like disease." (PMID 27747498, 2015). "ICOS+PD-1+CXCR5+CD4+ T cells are correlated with the functional properties of Tfh cells and play a role in severe systemic lupus erythematosus (SLE)." (PMID 26517519, 2015). "It is increasingly evident that various environmental triggers of SLE skew lupus CD4+ T-cells towards autoreactivity by altering the epigenetic mechanisms." (PMID 25216337, 2014).
lupus (continued). "TRIM22 expression is also downregulated in CD4+ T cells from patients with active systemic lupus erythematosus (SLE)." (PMID 22649727, 2012). "Moreover, in two models of systemic lupus erythematosus, PI3Kγ was shown to control the CD4+ memory T cell reservoir mostly in the context of a second genetic alteration (MRL-lpr or p65PI3KTg), while single-targeted PI3Kγ-inhibition revealed only modest phenotypes." (PMID 20374644, 2010). "The senolytic drug ABT-263 (Navitoclax), which effectively depletes senescent CD4+ T cells, senescent B cells (CD19+CD11c+T-bet+), and Tfh cells, significantly reduced these populations in lupus-prone MRL/lpr mice." (PMID 40852730, 2025). "CD11b B1 cell frequency was significantly elevated in lupus patients, and they expressed a higher level of CD86, thus facilitating the stimulation of CD4 T cells." (PMID 39960645, 2025). "Used as a mouse model of lupus and Sjogren’s syndrome, BAFF-overexpressing mice (BAFF-Tg) have increased numbers of peripheral Foxp3+ CD4 Tregs with concomitant expansion of B2 cells, which is associated with the development of autoimmunity." (PMID 40625741, 2025). "We also considered the possibility that CXCR5low CD4+ T cells might be peripheral T helper cells (Tph), a population postulated to be tissue‐resident counterparts of Tfh cells that has been reported in some patients with rheumatoid arthritis and systemic lupus erythematosus." (PMID 40469525, 2025). "A characteristic of CD4+ T cells from SLE patients and lupus‐prone mice is increased glycolysis." (PMID 40976999, 2025). "In systemic lupus erythematosus, the upregulation of CD38 and HLA-DR on CD4+ and CD8+ T cells signifies a state of chronic immune activation." (PMID 40370439, 2025). "The imbalance and abnormal function of CD4+ and CD8+ T cells have important functions in the regulation of the development of systemic lupus erythematosus." (PMID 40427615, 2025). "There was a trend for DON reducing the high frequency of W.Yaa effector memory T cells (CD4+CD44+CD62L– Tem), leading to a significantly decreased Tem/CD4+CD44–CD62L+ naive T (Tn) cell ratio, which is typically elevated in lupus-prone mice." (PMID 40956613, 2025). "Probiotics such as L. delbrueckii, L. rhamnosus, L. reuteri, and L. acidophilus induce CD4+CD25+Foxp3+ Tregs and suppress Th17 cells in lupus models via metabolite-mediated signaling pathways." (PMID 40534849, 2025). "Dual metabolic hyperactivation in SLE CD4+ T cells drives pathogenicity; combined glycolysis and OXPHOS inhibition reverses lupus in mouse models." (PMID 41476956, 2025). "Interestingly, UC-derived MSCs alleviate the energy starvation of CD4+T cells by transferring mitochondria to T cells by downregulating the autophagic process and apoptosis of CD4+T cells, which plays an important role in the treatment of systemic lupus erythematosus." (PMID 39010157, 2024). "mTORC1 activation of CD3+, CD4+, and CD8+ T cells of lupus-prone B6.TC/Rab4AQ72L mice was reversed by the inactivation of Rab4A in T cells of B6.TC/Rab4AQ72L-KO mice." (PMID 38519468, 2024). "Purified human CD4+ T cells stimulated with anti-CD3 and anti-CD28 antibodies exhibited robust production of lupus-related pro-inflammatory cytokines (e.g., IFN-γ, TNF-α, IL-5, and IL-6) upon anti-CD3/CD28 beads stimulation." (PMID 39551768, 2024). "However, CD4+ T cells seem to play a decisive role, since their characteristic decline and activation was ascertained in both SLE patients and lupus-prone mice." (PMID 38427068, 2024). "In response to Rab4A-driven lupus pathogenesis, mTORC1 was consistently activated in CD3+, CD4+, and CD8+ T cells of 20-week-old B6.TC/Rab4AQ72L mice relative to B6/Rab4AQ72L controls." (PMID 38519468, 2024).
lupus (continued). "Our data suggest that basophils deliver the required IL-4-induced priming to CD4+ T cells in a PD-L1-dependent manner that allows TFH and TFH2 cell accumulations in the lupus-like context." (PMID 38649353, 2024). "Along with lupus-like autoimmune disease, Qa-1-restricted CD8 Tregs directly regulated autoreactive CD4 T cells in an experimental autoimmune encephalomyelitis (EAE) model." (PMID 37907738, 2023). "There was a common hypomethylation of type I IFN signature genes in CD4+ T cells, CD19+ B cells, CD14+ monocytes, and neutrophils, resulting in heightened type I IFN signaling in human patients with lupus." (PMID 38153351, 2023). "In systemic lupus erythematosus (SLE), the overexpression of miR-21 and miR-148a in CD4+ T cells contributes to DNA hypomethylation by repressing DNMT1." (PMID 37239435, 2023). "In our study, we found that MSCs regulate circulating miR-320b and miR-320b/MAP3K1 expression to restrain CD4+ T-cell proliferation in SLE and lupus mice." (PMID 37928434, 2023). "Endogenous peptide epitopes of histones from nucleosomes induce immune tolerance and promote CD4+ and CD8+ Treg responses, and reduce lupus nephritis and B cell activation in (SWR x NZB) F1 (SNF1) mice, also blocking pathogenic autoimmunity in human SLE." (PMID 37781681, 2023). "Another study reported that CD4+CXCR5−CXCR3+PD-1hiIFN-γ+IL-10+ cells with a phenotype similar to that of Tph cells exist in the peripheral blood and lupus nephritic tissues of patients with SLE." (PMID 37371540, 2023). "Dalazatide, a Kv1.3 channel inhibitor currently in clinical trials, has been reported to reduce inflammatory cytokines such as IFN-γ, IL-17, and TNF–α in CD4+ and CD8+ T cells from patients with systemic lupus erythematosus (SLE)." (PMID 37033961, 2023). "We observed that pharmacological inhibition of METTL3 by STM2457 promoted CD4+ T-cell activation and reduced the population of Treg cells in a humoral SRBC model and lupus-like cGVHD model." (PMID 37013484, 2023). "Agonistic monoclonal antibody (mAb) specific to Lrig1 or adoptive transfer of CD4+Lrig1+ T cells exhibits significant therapeutic efficacy in experimental autoimmune encephalomyelitis (EAE), IBD, and lupus animal models." (PMID 37666819, 2023). "Traditionally, autoimmune pathogeneses have been attributed to CD4(+) T lymphocytes, as in MS, rheumatoid arthritis, and DMII, and to B lymphocytes, as in myasthenia gravis and systemic lupus erythematosus." (PMID 37568348, 2023). "The expression of markers of T cells (CD4, CD8α), B cells (CD19) and macrophages (CD68) was elevated in PVAT from lupus mice." (PMID 37006244, 2023). "A previous report showed that the expression of ICOS on the surface of CD4+ T cells and soluble ICOS in the peripheral blood of patients with systemic sclerosis and systemic lupus erythematosus are significantly increased." (PMID 35723338, 2022). "This study explored the correlation between peripheral blood CD3+, CD3+/CD4+, CD3+/CD8+, CD4+/CD8+, CD3−/CD16+ CD56+, and CD3−CD19+ and disease activity of different subtypes of systemic lupus erythematosus (SLE)." (PMID 36045722, 2022). "In vitro, IFN-I were shown to prolong survival of CD4+ T cells, and in a non-lupus model, IFN-I enhanced the clonal expansion of antigen-specific CD4+ T cells by increasing survival signals and leading to increased numbers of IFNγ producing cells." (PMID 35055071, 2022). "These subclasses are derived from different human peripheral blood samples representing different disease states, such as naive CD4+ T cells in peripheral blood derived from healthy individuals (PB_naiveCD4T_normal) or systemic lupus erythematosus (SLE) patients (PB_CD4Tnaive_SLE)." (PMID 35363305, 2022). "After PF intervention, the inflammatory cytokines in splenocytes and CD4+ T lymphocytes of MRL/lpr mice decreased significantly, which was consistent with our previous study of PF on peritoneal macrophages in lupus mice." (PMID 36467552, 2022).
lupus (continued). "Taken together, our data indicate that IL-39 infusion enhances T cell activation and GC B cell differentiation, while reducing the proportion of CD4+CD8+ double-positive cells in the thymus, thereby aggravating lupus-like cGVHD." (PMID 35655245, 2022). "The oetiology of SLE remains unclear, but earlier research has revealed a pivotal function of CD4+ T cells in lupus pathogenesis." (PMID 35343082, 2022). "To downregulate the expression of miR-21 in lupus CD4+ T cells and evaluate the effect on Tfh cell differentiation, we isolated CD4+ T cells from peripheral blood of patients with SLE and transfected them with Antagomir-21 and then stimulated them with anti-CD3/CD28 antibodies for two days." (PMID 35499082, 2022). "Therefore, our findings identified 6 novel potential biomarkers in lupus CD4+ T cells, which provided new insights into the development and treatment of SLE." (PMID 36046235, 2022). "EZH2 is overexpressed in CD4+ T and CD19+ B cells of lupus patients and promotes the adhesion, migration, extravasation of CD4+ T cells, and plasmablast differentiation." (PMID 35795677, 2022). "We found that in the pristane-induced lupus mouse model, mice fed with LID showed the fewer frequency and number of CD4+ IL17A+ Th17 cells and the lower ratio of Th17/Treg cells compared with the ND controls." (PMID 35296076, 2022). "HTO deconvolution demarcated cells based on T cell type (i.e., CD4 and CD8), organ of origin (kidney vs. spleen), and potential autoreactive status (B6 vs. lupus-prone mice)." (PMID 35271505, 2022). "Recently, it was demonstrated that in systemic lupus erythematosus (SLE) patients, interferon-regulated genes are hypomethylated in naïve CD4+ T cells, CD19+ B lymphocytes, and CD14+ monocytes." (PMID 36429769, 2022). "A positive correlation between the frequencies of TSCM CD4+ and CD8+ cells is seen in AA, autoimmune uveitis and systemic lupus erythematosus (SLE)." (PMID 35784300, 2022). "Inhibiting DNMTs in CD4 and CD8 T cells with 5-azaC and a nanolipogel delivery system dramatically ameliorates lupus-related pathology through distinct mechanisms." (PMID 36220996, 2022). "RSV inhibits IgG levels in pristane-induced lupus mice, B cell proliferation, and antibody production in vivo; RSV induces CD4+ T cell apoptosis and the percentage of Th1 cells and decreases the ratio of Th1/Th2 cells in vitro." (PMID 33981300, 2021). "Increased OXPHOS and glycolysis have also been reported in CD4+ T cells from both SLE patients and lupus prone mice." (PMID 33790300, 2021). "In patients with active systemic lupus erythematosus (SLE), the proportion of CD4+BTLA+ T cells is markedly decreased." (PMID 33859648, 2021). "Consistent with our studies in the NZBWF1 model, as well as previous studies in pristane‐induced lupus, we detected increased CD45+ and CD4+ T cells in the kidney." (PMID 33527772, 2021). "This epitope is recognized by IgG antibodies and CD4+ T cells from H‐2k MRL/lpr and H‐2d/z (NZB × NZW)F1 lupus‐prone mice." (PMID 34335564, 2021). "We did not detect significant ex vivo variations of BTLA expression on total CD4+ T cells (naive and memory), cTFH or TFH subsets between lupus patients and healthy controls." (PMID 34899718, 2021). "Thus, miR-125a may play a part in lupus CD4+T cells by targeting the 3′-UTR of KLF13." (PMID 33750387, 2021). "To assess the regulatory role of CD38 in T-cells from a lupus-prone mouse (B6.MRL-Faslpr/J), we examined FoxP3 expression in three different subsets of CD3+CD4+CD25+ and CD3+CD4+CD25− T-cells, gated according to CD38 expression." (PMID 34769406, 2021). "Specifically, the NPs promoted a switch to tolerogenic responses with an induction of CD4+ and CD8+ Tregs that were responsible for the mitigation of disease manifestations and prolonged the survival of BDF1 lupus mice." (PMID 34122401, 2021).